CD4 (CD4 molecule)
Diseases named in the same sentence as CD4 in open-access papers (continued):
Sharing a sentence is not in itself a finding about the gene and the disease.
infection (continued). "Compared with the ratio of CD4+/CD8+ at 6 h, it was significantly decreased at 30 h after infection." (PMID 31855175, 2019). "Cell type-specific analysis revealed that natural killer (NK) cell, neutrophil, antigen-presenting cell (APC), and CD4 and CD8 T cell counts were increased upon RSV infection compared to those of mock infection for both inoculation methods." (PMID 31163619, 2019). "At day 6 post infection, T-bet expression in TFH and TH1 cells was upregulated to nearly 8- and 24-fold, respectively, compared to that in naïve CD4+ T cells." (PMID 30984183, 2019). "Here we studied CD4 +T cells purified from PBMCs of 131 EC/VCs and identified a subset of HIV EC/VCs whose T cells were relatively resistant to infection by R5-tropic pseudotyped viral particles, in single cycle, cell-based in vitro assays." (PMID 30964004, 2019). "The time-course of infection and the 72-h infection by HIV-1 significantly increased MALAT1 expression in all these CD4+ T-lymphocyte cell types." (PMID 30788509, 2019). "The main players are CD4 and DC-SIGN, leading the first one to conventional infection and the latter to either trans-infection or Ag presentation." (PMID 31708924, 2019). "Elles étaient d'autant plus anormales avec ceux ayant un moins contrôle de l'infection à VIH CD4 < 350 dans 75% des cas contre 69,2% de patients avec CD4 = 350 éléments/mL)." (PMID 31762909, 2019). "In order to demonstrate that CD4+ TRM from cervix represent a significant cellular reservoir, we first aimed to address if this subset supports infection ex vivo and which are the dynamics of CD69 after HIV infection in these tissues." (PMID 31628331, 2019). "CD4 TCM cell frequencies, on the other hand, were diminished similarly in WT and KO mice post-infection." (PMID 31736943, 2019). "For instance, the surface of naïve CD4+ T-cells express very low levels of CCR5, an HIV-1 co-receptor, which results in the restricted infection by R5-trophic viruses." (PMID 31487807, 2019). "The polyfunctional IFN-γ- and IL-17-producing CD4+ T cells in the middle ear of transcutaneous immunized chinchilla, an established model of AOM, clear the NTHi infection." (PMID 31548315, 2019). "In contrast to B cell infection in IM, CAEV features the proliferation and infection of polyclonal, predominantly non-CD8+ (CD4+CD8− and CD4+CD8+) T cells, and CD16+ natural killer (NK) lymphocytes." (PMID 31783813, 2019). "In the study presented here, sublancin increased the frequencies of naïve CD4+ and CD8+ T cells, as well as memory CD8+ T cells in MLNs at 36 hours after infection." (PMID 31583256, 2019). "As expected, the frequency of CD3+CD4+Foxp3+ T cells increased in the PLN after 7 and 14 days post-infection." (PMID 31611578, 2019). "The number and function of CD4+, CD8+ T cells, or NK cells in all four patients were decreased in a different degree when infection occurred." (PMID 31857499, 2019). "The effect was more striking with lung tissue-resident CD4 T cells from convalescent mice, which is consistent with the view that TRM cells are more effectively generated by infection or immunization at mucosal surfaces." (PMID 30866771, 2019). "The study reveals that the percentage of CD4+CD25+ and CD4+ FoxP3+ T cells were progressively enhanced until 4 months of infection compared to control naïve mice." (PMID 31031744, 2019). "These cells also express higher amounts of CCR5 on their surface compared to LCs, are more permissive for infection with HIV and more efficient at transferring HIV to CD4 T cells." (PMID 31227717, 2019). "Altogether, our results indicate a decrease in EM and Tfh cell subsets during the acute phase of the infection, which is more drastic in chronically SIV-infected RMs with low levels of CD4 T cells in MLNs." (PMID 31114010, 2019). "IL-2 induces CD4+ and CD8+ T cells proliferation and differentiation, and promotes the development of memory T cells during primary infection." (PMID 31552037, 2019).
infection (continued). "At day 3 post infection, T-bet expression in TFH and TH1 cells was ~2- and 4-fold higher, respectively, than that in naïve CD4+ T cells." (PMID 30984183, 2019). "A significant difference (p ≤ 0.05) for days post infection and treatment status (VEH vs. Δ9-THC) was detected for CD4+/PD-1+ measurements." (PMID 31114576, 2019). "Upon CD4+ T cell infection, expression of the HIV Nef gene product drives the rapid downregulation of CD4 from the surface of the infected cell." (PMID 30903381, 2019). "The representative dot-plot graphs show ~42% myc tag positive cells in both CD4+ and CD8+ human primary T cells by day 12 after infection." (PMID 31514488, 2019). "With additional transcriptional studies of HCV-specific CD4 and CD8 T-cells in different stages of infection currently underway, we expect HCV infection to become a valuable model disease to study human immunity to viruses." (PMID 31357397, 2019). "Histological analysis past the second week of infection also revealed unexpected findings that help to explain the cause of virus-associated death in SCID hosts, and that might suggest a novel role for memory CD4 T cells in regulating lung epithelial proliferation." (PMID 30641955, 2019). "Additional studies using a high-dose aerosol (HDA, approximately 1,000 bacilli per mouse) in C57BL/6 and Ob/Ob mice have resulted in an established infection and an early pulmonary influx of IFN-γ+ CD4+ T cells." (PMID 30763316, 2019). "Mice depleted of both CD4+ and CD8+ T cells were unable to control infection and showed signs of severe disease, similar to the findings for the naive infection controls (P > 0.05)." (PMID 30323025, 2019). "During infection, KCC1M935K/M935K had a slight increase in the average amount of CD4+ T cells in the blood compared to WT." (PMID 31015511, 2019). "Infection with HIV induces immune suppression and depletion of CD4 T cells, which play a critical role in limiting Mtb bacterial growth and reducing progression to active TB disease." (PMID 31497018, 2019). "Here, we investigated the infectivity of these viruses in isolated, primary human resting CD4+ T cell subsets (TN, CCR5− TM, and CCR5+ TM) in a dual-infection model." (PMID 31036079, 2019). "Compared to porcine reproductive and respiratory syndrome virus and porcine circovirus type 2, only SwIAV generates a significant increase in CD4 and CD4CD8 cells in the BAL of infected animals suggesting a role for this population during infection." (PMID 30804933, 2019). "Relevantly, here we show that only CD4+ and CD8+ cells from BALB/c mice showed an infection-induced increase capacity of secreting IL-10, which is retained at 8 weeks post-infection." (PMID 30881923, 2019). "During the acute phase of infection, brain infiltrating CD25+ FoxP3+ CD4+ T cells were found to express PD-1." (PMID 31105690, 2019). "Using a conditional knockout model, we show that Add1 is necessary for complete activation of CD4+ T cells in response to low levels of antigen but is dispensable for CD8+ T cell activation and response to infection." (PMID 31824498, 2019). "In both humans and mouse models of infection, ZIKV induces robust T cell activation, which leads to the establishment of a memory T cell population, suggesting an important role for CD4 and CD8 T cells in the immune response to ZIKV." (PMID 31382545, 2019). "CD4 and CD8 T cell responses were very low or negligible for rapid progressors at week 4 of infection with the exception of one cat." (PMID 31118053, 2019). "While DCs work to promote an efficient immune response and halt the infection, HIV-1 has ways to take advantage of their role and uses DCs to gain faster and more efficient access to CD4+ T cells." (PMID 31708924, 2019). "Increased Glut1 expression on CD4 T cells in culture increases cellular permissivity to HIV-1 infection, while suppression of glucose metabolism by PI3K inhibitors inhibits infection." (PMID 31921023, 2019).
infection (continued). "Like CD4 T cells, CD8 T cells differentiate into multiple subsets that are customized to a specific infection and immune settings." (PMID 31275308, 2019). "In naïve mice, 12% of CD4+ T cells and 9% CD8+ T cells were labeled by Ki67, but more than 30% of CD4+ T cells and 16% of CD8+ T cells expressed Ki67 following CVCC541 infection." (PMID 30898022, 2019). "In this review, we will discuss the CD4 and CD8 T cell responses to ZIKV, and the lessons we have learned from both mouse and human infections." (PMID 31382545, 2019). "Our previous studies of FT in the murine model showed IFNγ expression by CD4, CD8 and NK cells in the respiratory system as early as two days post intranasal infection." (PMID 31443439, 2019). "We did not specifically examine the microenvironmental positioning of Ag-specific CD4+ vs. CD8+ T cells, which has been reported to differ depending on the infection model used." (PMID 31552034, 2019). "As innate TNF-α dependant mechanisms drive cell mediated immunity by activation of CD4+ and CD8+ T cells, TNF-α is known to be fundamental in the initial control of the infection together with other cytokines such as IL-12 and IFN-γ." (PMID 31469834, 2019). "In memory CD4 T cells infected with HIV in vitro, two distinct infected populations of p24+CycT1+ and p24+CycT1- cells were observed during 7 days infection, suggestive of different phases of productive HIV replication and subsequent latency establishment." (PMID 30786885, 2019). "Intravenous and intravaginal infection with ZIKV effectively induced follicular helper and regulatory CD4+ T cells." (PMID 30677097, 2019). "The second phase of transfer occurs as a result of CD4/CCR5 mediated productive infection and begins to occur within 72 h of infection and increases with time as newly formed virions bud off from the plasma membrane." (PMID 31227717, 2019). "HeLa-CD4 cells were infected with WT, MUT1, and MUT2 viruses, and 9 days after infection, cells were analyzed by ChIP." (PMID 31266880, 2019). "B8 and B5 antigens are expressed by various VACV strains including MVA and served as infection controls and helped to validate the efficacy of recMVA vaccination comparative to MVA-wt for CD8+ and CD4+ T cells, respectively." (PMID 31921215, 2019). "Secretion of IL-4 of T lymphocytes from the WT-INF group (CD4: 8.01 ± 1.23%; CD8: 2.1 ± 0.23%) was also higher than TLR7-INF (CD4: 1.43 ± 0.48%; CD8: 0.94 ± 0.14%, P < 0.05) after infection." (PMID 31930147, 2019). "After the infection with DENV2, all E-derived peptides induced a TNF-α response in CD4+ and CD8+ T cells collected from pE1D2-vaccinated animals, except for CD8+ T lymphocytes stimulated with the peptide E98." (PMID 31333657, 2019). "CD4+ Th1 T-cell-produced IFN-γ and TNF-α can activate bystander resting macrophages and prevent their infection by MTB." (PMID 30625198, 2019). "Cytotoxic CX3CR1+ CD4+ T-cells also play a protective role during DENV infection and immunization with CD4+ T-cell epitopes prior to infection contributes to viral clearance after subsequent viral challenge in IFN-α/βR−/− mice." (PMID 30678246, 2019). "Cells were separated using AFMACS at the indicated time points post-infection with HIV-AFMACS, stained with anti-LNGFR and anti-CD4 antibodies and analysed by flow cytometry." (PMID 30857592, 2019). "CD4 T cells, also known as helper T cells, assist CD8 T cell-mediated cellular immunity and B cell-mediated humoral immunity in antivirus infection." (PMID 30733641, 2019). "All BRAI-invalid samples were classified as recent infections, which is supported by the high HIV-1 VLs and CD4+ T cell counts of these samples." (PMID 31125356, 2019). "T cells were gated with a primary gate on viable FSClow vs. SSClow lymphocytes and then on CD3+ T cells and compared to the isotype controls, and analyzed for changes in the total mean cell number of CD3+CD4+ and CD3+CD8+ cells over the course of infection." (PMID 31001241, 2019).
infection (continued). "The work detailed herein offers new insights into the endogenous CD4 T cell response in the lungs of BALB/c and C57Bl/6 mice during infection with IAV." (PMID 31632414, 2019). "Despite the extraordinary ability to naturally suppress HIV-1 viremia, a proportion of EC exhibit a CD4+ T cell counts decline (immunologic progression) and/or lose their ability to control HIV (virologic progression) over the course of infection." (PMID 31001238, 2019). "Two days post infection, cells were labelled with fluorescein-conjugated anti-CD3, anti-CD4 and anti-CD8 antibodies, and analyzed with flow cytometry." (PMID 31014302, 2019). "It is remarkable that in other infectious processes, CD4+CD25+ Treg and IL-10 protect against the infection or the disease." (PMID 31481953, 2019). "Specifically, transcription of Cxcl10 is upregulated in T resident-memory (Trm) cells after secondary infection, and antibody blockade of CXCR3 prevents recruitment of circulating CD4+ T cells to the site of infection." (PMID 31440475, 2019). "In the current study as we observe maternal CD4+ count of >200cell/mm3 in mothers that are HIV positive, we can conclude that infection can be transmitted from these mothers to the exposed infants." (PMID 31349803, 2019). "Lower parasite load in the cardiac tissue resulted in decreased levels of CCL5, a chemokine that is important for the recruitment of both CD4+ and CD8+ T cells effector cells to the site of infection." (PMID 31197200, 2019). "Nine days after infection, which is the height of the T cell response to IAV, we determined the number and percentage of proliferating CD4+ T cells using the marker Ki67." (PMID 31391494, 2019). "CD4+ T cells and CD11b-CD11c+ alveolar macrophages were significantly enhanced only in Mtb-LT1 infection." (PMID 30840702, 2019). "In the case of pDCs, infection with HIV-1 seems to turn these cells more tolerogenic, and increase their potential to drive polarization of CD4+ T cells into immunosuppressive T regulatory cells." (PMID 31244850, 2019). "Infection of DCs and macrophages is particularly important as they are uniquely poised to transmit HIV with high efficiency to CD4+ T cells during antigen presentation within the secondary lymphoid organs." (PMID 31396206, 2019). "Univariate analysis for these variables confirmed a significant positive correlation between the acquisition of infection and pre-challenge ADCVI activity, Env-specific TNF-α+ CD4 T cells or Env-specific IFN-γ+ TNF-α+ cells." (PMID 30778066, 2019). "While the F3 vaccine determines an earlier trigger of the development of the CD4+ and CD8+ T cell responses, the F1F3 was more efficient in long-term infection." (PMID 31024556, 2019). "At inclusion, the median age was 51 [IQR: 44–55] years; the median duration of known infection was 12.6 [IQR: 9.1–22.8] years and median CD4 T-cell count was 966 cells/μL [IQR: 820–1216]." (PMID 31095640, 2019). "In this study, we found that PCV2 induced the reduction of splenic CD4+ and CD8+ T cells at late phase of infection in wild-type mice, and increased the pulmonary CD4+ and CD8+ T cells." (PMID 31551984, 2019). "A significant difference (p ≤ 0.05) for days post infection and treatment status (VEH vs. Δ9-THC) was detected for CD4+/CD8+/Ki67+ measurements." (PMID 31114576, 2019). "We observed that E-30 infection enhances the migration of CD3+, CD4+, and CD8+ naive T cells across the BCSFB, especially once CXCL12 is apically present." (PMID 31752904, 2019). "The protective mechanism of HIV-specific CD4+ T cells is less clear than CD8+ T cells, especially since HIV-specific CD4+ T cells are preferentially infected and depleted by HIV during infection." (PMID 31449552, 2019). "Although the immune mechanisms involved in the control of CHIKV disease are not fully characterized, CHIKV-infected humans show different timing of CD4+ and CD8+ T cell responses in the acute phase of infection." (PMID 31276466, 2019).
infection (continued). "At day 40, 90, and 160 post infection, T-bet expression in TFH and TH1 cells had further decreased and remained ~4- and 6-fold higher, respectively, than that in naive CD4+ T cells." (PMID 30984183, 2019). "These co-cultures have been used to measure drug and Ab activity against trans infection between primary mature DCs (mDCs) and TZM-bl cells or autologous CD4+ T cells and between primary iDCs and PM-1 cells." (PMID 31178736, 2019). "Thus, the study clearly depicts that Dectin-1 essentially contributes to the stability of Th1, Th17, Treg CD4+ T-cell populations during infection, as its deficiency lead to defective release of Th17 cells in C57BL/6 mice and both Th1 as well as Treg cells in BALB/c mice after infection." (PMID 31555269, 2019). "The patient who died of disseminated M. haemophilum infection was a 25-year-old man who was given a new diagnosis of infection with HIV and had a CD4 cell count of 17 cells/mm3." (PMID 31441427, 2019). "Mice receiving PBS succumbed to infection at 4 dpi, while CLH001-immunized mice replete with T cell (isotype control) as well as CLH001-immunized mice depleted of CD4+ and CLH001-CD8+ T cells showed 100% survival at 16 dpi." (PMID 31306423, 2019). "Despite increased CD4 T cell cytotoxicity, CD8 T cells responding to AE promoted dendritic cell (DC) maturation and CD4 T cell trans-infection perhaps explaining why AE are predominant in CHI." (PMID 31398241, 2019). "The recruitment of CD4+ or CD8α+ T cells to the brain was unchanged in T. gondii-infected and co-infected mice (MANOVA with cell type as dependent variable and infection status as fixed factor: F2, 7 = 2.65, Wilks’ Λ = 0.569, p = 0.139)." (PMID 31352901, 2019). "Chronic hepatitis C virus (HCV) infection is characterized by increased proportion of CD4+CD8+ double positive (DP) T cells, but their role in this infection is unclear." (PMID 30972915, 2019). "Along with CD4+ T cells, mouse studies show that CD8+ T cells play a role in protection against infection with Coccidioides." (PMID 31572393, 2019). "We compared the four vaccines and observed that the F3 formulation determined a significant enhancement of frequencies of CD4+ and CD8+ secreting-T cells after immunization, while the chimera vaccine was predominant for both types of T cells after infection." (PMID 31024556, 2019). "Initiation onto ART soon after the initial infection with HIV and prophylactic use of trimethoprim-sulfamethoxazole with all baseline CD4 cell counts < 350 cells/mm3 are recommended." (PMID 31956436, 2019). "The primary reservoirs of HIV latently infected cells are thought to be long-lived, resting central memory CD4+ T cells (TCM), which are established early in infection, harbor integrated proviral DNA, and fail to produce replication-competent virus." (PMID 31142734, 2019). "Following infection, VRC01-Rh-α4β7-treated macaques maintained higher CD4+ T cell counts and exhibited lower rectal SIV-DNA loads compared to controls." (PMID 31083697, 2019). "Activated CD4+ T cells more readily support productive HIV replication, potentially rendering them more vulnerable to infection in any HIV cure attempt involving analytic treatment interruption (ATI)." (PMID 30863403, 2019). "The ELLAITTVVGNQ and DVAGIVGPVAAGCT peptides of F1 acted more on cytokine secretion by CD4 and CD8 T cells before infection while the FRYPRPKHCCHTQVA, KFWCLVIDALKRIG did that after challenge." (PMID 31024556, 2019). "Although we found the frequencies of CD4+ Foxp3+ Tregs to be comparable in the gastric LP of WT and BATF3-/- mice, both in the steady state and upon infection, the composition of the Treg compartment differed substantially as a result of BATF3 deficiency." (PMID 31188899, 2019). "In kidney transplant recipients, the number and function of CD4+ and CD8+ T cells were increased or decreased when rejection or infection occurred." (PMID 31857499, 2019).